GBE1 (1,4-alpha-glucan branching enzyme 1)
Description:
Glycogen-branching enzyme participates in the glycogen biosynthetic process along with glycogenin and glycogen synthase. Generates alpha-1,6-glucosidic branches from alpha-1,4-linked glucose chains, to increase solubility of the glycogen polymer.
Synonyms: APBD; GBE; GSD4
Tractability: Small molecule: a structure with a bound ligand is known. PROTAC: ubiquitination databases record sites on it; its protein half-life has been measured.
Gene: Protein-coding gene on chromosome 3 (81,489,699 to 81,761,781, reverse strand). Ensembl gene ENSG00000114480.
Subcellular location (Human Protein Atlas): Cytosol
Pathways (Reactome):
Disease: Glycogen storage disease type IV (GBE1)
Metabolism: Glycogen synthesis
Gene Ontology:
Molecular function: 1,4-alpha-glucan branching enzyme activity; protein binding; catalytic activity; cation binding; hydrolase activity, hydrolyzing O-glycosyl compounds
Biological process: glycogen biosynthetic process; generation of precursor metabolites and energy; glycogen metabolic process; carbohydrate metabolic process
Cellular component: extracellular exosome; cytoplasm; cytosol
Genetic constraint (gnomAD): Loss-of-function variants: 26 observed, 29.78 expected, observed/expected ratio (o/e) 0.87, 90% interval 0.64 to 1.21. The upper end of that interval is the gene's LOEUF score, 1.21, which puts it in group 5 of 6, group 1 being the genes least tolerant of losing a copy. Missense variants: 420 observed, 415.79 expected, observed/expected ratio (o/e) 1.01, 90% interval 0.93 to 1.1. Synonymous variants: 145 observed, 150.26 expected, observed/expected ratio (o/e) 0.97, 90% interval 0.84 to 1.11.
Gene-disease validity (ClinGen):
ClinGen rates the evidence that GBE1 causes each of these diseases.
glycogen storage disease due to glycogen branching enzyme deficiency (autosomal recessive): Definitive. Glycogen branching enzyme (GBE) deficiency (Andersen's disease or amylopectinosis), or glycogen storage disease type 4 (GSD4), is a rare and severe form of glycogen storage disease which accounts for approximately 3% of all the glycogen storage diseases.
Homologues: Orthologues: chimpanzee GBE1 (99% identical), macaque GBE1 (95% identical), mouse Gbe1 (91% identical), rat Gbe1 (91% identical), dog GBE1 (90% identical), rabbit GBE1 (89% identical), guinea pig GBE1 (82% identical), pig GBE1 (79% identical), tropical clawed frog gbe1 (75% identical), zebrafish gbe1b (70% identical), zebrafish gbe1a (64% identical), Drosophila melanogaster AGBE (60% identical), and 1 more. Paralogues in human: SLC3A1 (14% identical), SLC3A2 (12% identical), AMY1A (11% identical), AMY1B (11% identical), AMY1C (11% identical), AMY2A (11% identical), AMY2B (11% identical).
Diseases named in the same sentence as GBE1 in open-access papers:
GBE1 is named in the same sentence as 86 diseases in open-access papers, as found by Europe PMC text mining. Sharing a sentence is not in itself a finding about the gene and the disease. The quoted sentences say what the papers report.
Glycogen storage disease type IV (31 papers, 2011 to 2026). "Glycogen storage disease type IV (GSD IV) is an autosomal recessive disorder caused by pathogenic variants in GBE1, resulting in deficient glycogen branching enzyme (GBE) activity and formation of abnormal glycogen ("polyglucosan")." (PMID 41948007, 2026). "The patient with GBE1 variants, who had severe glycogen storage disease type 4, experienced respiratory failure from birth and required full ventilatory support." (PMID 40494860, 2025). "Among the known GSDs, GSD type IV (Andersen disease), is a clinically heterogenous disorder caused by deficiency of glycogen branching enzyme 1 (GBE1)." (PMID 41044641, 2025). "Glycogen storage disease type 4 (GSD IV) (OMIM 232500) is a rare autosomal recessive disorder caused by pathogenic mutations in the GBE1 gene located on chromosome 3." (PMID 40909175, 2025). "Glycogen Storage Disease Type IV (GSD-IV) is another disorder caused by pathogenic biallelic variants in the GBE1 gene." (PMID 40176792, 2025). "Compound heterozygous or homozygous variants in the GBE1 gene have been also associated with myopathic, hepatic, and cardiomyopathic involvement seen in glycogen storage disease type IV (Andersen disease)." (PMID 40757593, 2024). "The branching enzyme deficiency (GBE1 gene, chromosome 3p14) causes the GSD type IV or Andersen disease." (PMID 35725468, 2022). "In horses, one of these deleterious mutations is the 102C > A nonsense mutation in the first exon of the GBE1 gene, which causes the condition known as Glycogen Branching Enzyme Deficiency (GBED)." (PMID 32366884, 2020). "GSD type IV, also known as Andersen disease, results from mutations in the GBE1 gene, causing a deficiency in the glycogen branching enzyme, which adds branches to the growing glycogen molecule during the synthesis of glycogen, allowing for easy and quick glycogen utilization when it is broken down." (PMID 37601653, 2023). "The GBE1 gene belongs to the glycosyl hydrolase 13 family, whose mutations can cause adult polyglucosan body disease (APBD), which is a fatal adult-onset neurodegenerative disease featuring progressive sensory deficits and upper and lower motor neuron dysfunction." (PMID 36831718, 2023). "Mutations in GBE1 can cause autosomal recessively inherited adult Polyglucosan body disease (APBD) which is characterized by upper motor neuron signs similar to ALS, early neurogenic bladder, cognitive impairment and decreased or absent activity of the glycogen branching enzyme." (PMID 27790088, 2016). "Glycogen storage disease type IV (GSD IV—OMIM #232500) is a hepatomuscular inborn error of the metabolism caused by a deficiency of glycogen branching enzyme (E.C. 2.4.1.18), encoded by GBE1." (PMID 36830903, 2023). "Pathogenic variants in the GBE1 gene are linked to both APBD and Glycogen Storage Disease type IV (GSD-IV), both autosomal recessive disorders." (PMID 40176792, 2025). "Adult polyglucosan body disease (APBD) is a rare, adult-onset neurodegenerative disorder caused by loss-of-function variants in the glycogen branching enzyme (GBE1) gene, essential for glycogen biosynthesis." (PMID 40671519, 2025). "GBE1 mutations have been reported to be associated with adult polyglucosan body disease (APBD) and Glycogen Storage Disease Type IV (GSD IV)." (PMID 38961325, 2024). "Inadequate glycogen branching enzyme 1 (GBE1) activity results in different forms of glycogen storage disease type IV, including adult polyglucosan body disorder (APBD)." (PMID 38033781, 2023). "Andersen’s disease [OMIM:232500], or AR GSD type IV, is caused by mutations in the GBE1 gene at location 3p12, which encodes the glycogen branching enzyme (GBE, or 1,4-α-glucan branching enzyme type 1)." (PMID 37239976, 2023). "Glycogen storage disease type IV (GSD IV) is an ultra-rare autosomal recessive disease caused by variants in the GBE1 gene, which encodes the glycogen branching enzyme (GBE)." (PMID 36830903, 2023).
Glycogen storage disease type IV (continued). "Glycogen storage disease type IV (GSD IV), caused by a mutation in the glycogen branching enzyme 1 (GBE1) gene, is a rare metabolic disorder with an autosomal recessive inheritance that involves the liver, neuromuscular, and cardiac systems." (PMID 36425069, 2022). "In horses, the autosomal recessive condition known as Glycogen Branching Enzyme Deficiency (GBED) is the result of one of these deleterious mutations (102C > A), in the first exon of the GBE1 gene (GBE1102C>A)." (PMID 32366884, 2020). "Especially GBE1 is known to be related to glycogen storage disease type IV." (PMID 40001892, 2025). "Glycogen storage disease type IV (GSD IV; OMIM 232500) is an inborn error of metabolism caused by biallelic pathogenic variants in the GBE1 gene, which encodes glycogen branching enzyme (GBE), the enzyme responsible for forming branch points during glycogen synthesis." (PMID 38912588, 2024). "It is known that reduced levels of GBE1, as observed in GSD IV (Andersen disease), alters the structure of glycogen, affecting its solubility and resulting in accumulation of insoluble glycogen." (PMID 36111639, 2023).
adult polyglucosan body disease (20 papers, 2011 to 2025). Adult polyglucosan body disease (APBD) is a glycogen storage disease of adults characterized by progressive upper and lower motor neuron dysfunction, progressive neurogenic bladder and cognitive difficulties that can lead to dementia. "Adult polyglucosan body disease (APBD) is caused by mutations in the GBE1 gene encoding the glycogen branching enzyme protein (GBE1)." (PMID 40464291, 2025). "In a similar clinical context, in adult polyglucosan body disease (APBD), due to variants in the GBE1 gene, neuropathy, dysautonomia, parkinsonism, cognitive decline, and leukoencephalopathy can be observed in varying degrees in affected adult individuals." (PMID 40757593, 2024). "Polyglucosans form in a few diseases other than LD, including adult polyglucosan body disease (APBD), caused by deficiency of glycogen branching (GBE1)." (PMID 36511140, 2023). "Mutations in the GBE1 gene lead to the heterogeneous early-onset glycogen storage disorder type IV (GSDIV) or the late-onset adult polyglucosan body disease (APBD)." (PMID 26199317, 2015). "An adult male (F1.1) with a heterozygous GBE1 p.Tyr329Ser mutation associated with adult polyglucosan body disease (APBD), presented with distal paresthesias for 6 years, followed by erectile dysfunction, fatigue and progressive deterioration in vision in both eyes for 3 years." (PMID 34103343, 2021). "The loss of function of glycogen branching enzymes (GBE1) is the cause of glycogen metabolic disorders such as Glycogen Storage Disease IV (GSD–IV) and Adult Polyglucosan Body Disease (APBD)." (PMID 36900384, 2023).
lung adenocarcinoma (17 papers, 2017 to 2025). A carcinoma that arises from the lung and is characterized by the presence of malignant glandular epithelial cells. "GBE1 was found to cause promoter methylation of the FBP1 gene in lung adenocarcinoma cells through the NF-κB pathway, which decreased the expression of the FBP1 protein." (PMID 36900384, 2023). "The mutations in GBE1 have been reported with several types of cancers including lung adenocarcinoma and melanoma." (PMID 36268271, 2022). "This includes activating the expression of genes known to induce malignancy (ATAD2 (ATPase family AAA domain containing 2)) and genes that have been implicated in reduced survival in lung adenocarcinoma patients (GBE1 (glycogen branching enzyme), HK2 (hexokinase 2))." (PMID 36831404, 2023). "GBE1 expression is also elevated in lung adenocarcinomas and is associated with worse survival." (PMID 36900384, 2023). "However, the correlations between GBE1 expression and the prognosis and tumor-associated macrophages in lung adenocarcinoma (LUAD) also remain unclear." (PMID 35155189, 2021). "We previously found that glycogen branching enzyme (GBE1) is downstream of the hypoxia-inducible factor-1 (HIF1) signaling pathway in lung adenocarcinoma (LUAD) cells; however, the molecular mechanism underlying HIF1 regulation of GBE1 expression remains unknown." (PMID 32439898, 2020). "In lung adenocarcinoma, hypoxia-induced upregulation of GBE1 expression has been shown to promote tumor progression by regulating metabolic reprogramming." (PMID 39895786, 2025). "As one of the causes of glycogen metabolic diseases, recent studies have revealed that GBE1 affects the development and progression of a variety of tumors, such as leukemia, lung adenocarcinoma, and ovarian cancer." (PMID 36900384, 2023). "Our study found that FBP1 elevation by GBE1 knockdown suppressed the basal glycolytic rate and the glycolytic reserve capacity of glioma cells; this parallels a previous study on lung adenocarcinoma." (PMID 36900384, 2023). "In lung adenocarcinomas, GBE1 methylates the promoter of FBP1 through the NF-κB pathway and therefore decreases FBP1 expression." (PMID 36900384, 2023). "Glycogen Branching Enzyme 1 (GBE1)-mediated FBP1 suppression via promoter methylation contributes to tumor progression in lung adenocarcinoma (LUAD)." (PMID 35978816, 2022). "Previous studies reported that hypoxia-induced GBE1 expression promotes tumor progression by repressing FBP1 activities in lung adenocarcinoma." (PMID 34637697, 2021). "Knockdown of glycogen branching enzyme (GBE1) downstream of HIF1 in lung adenocarcinoma led to an increase in CCL5 expression and recruited more cytotoxic CD8+ T lymphocytes to contribute to tumor regression." (PMID 33312950, 2020). "Reportedly, lung adenocarcinoma-intrinsic glycogen branching enzyme (GBE1) antagonizes the expression and activation of STING." (PMID 33490069, 2020). "In the current study, we evaluated the correlation between lung adenocarcinoma (LUAD)-intrinsic GBE1 signaling and anti-tumor immunity, including T cell infiltration and PD-L1 regulation on tumor cells." (PMID 31221150, 2019). "In our previous study, lung adenocarcinoma-intrinsic glycogen branching enzyme (GBE1) signaling was found to inhibit antitumor immunity." (PMID 31775797, 2019). "We found that in patients with lung adenocarcinoma, expression of HK2 and GBE1 were positively associated with tumor size (P=0.0175, P=0.0018), tumor stage (P=0.00174, P=0.003) and TNM classification N staging (P=0.0256, P=0.0249), respectively." (PMID 28423489, 2017). "Studies have revealed that GBE1 expression is upregulated in hypoxia-conditioned primary lung adenocarcinoma cells mediated by HIF1α, while decreased GBE1 expression inhibits lung cancer cell growth by directly affecting glycogen production and glucose metabolic signaling pathways." (PMID 37601653, 2023).
lung adenocarcinoma (continued). "Previous studies demonstrated that hypoxia-induced GBE1 expression could promote tumor progression through metabolic reprogramming in lung adenocarcinoma (LUAD)." (PMID 35155189, 2021). "In the present study, we investigated whether GBE1 is involved in the immune regulation of the tumor microenvironment in lung adenocarcinoma (LUAD)." (PMID 31221150, 2019). "The survival analysis revealed that in lung adenocarcinoma patients, the ones with high expression of GBE1 and HK2 represented shorter overall survival than those with low expression of GBE1 (P=0.0332) and HK2 (P=0.0246), evidence supporting an association between these genes and cancer survival." (PMID 28423489, 2017). "High expression of the glycogen branching enzyme (GBE1), a key gene involved in the regulation of glycogen metabolism in lung adenocarcinoma, correlated with decreased overall survival and advanced TNM classification." (PMID 39199574, 2024). "In terms of prognostic features, a survival analysis revealed that the high GBE1 and HK2 expression group exhibited poorer survival in lung adenocarcinoma patients." (PMID 28423489, 2017). "We found that GBE1 and HK2 expression pattern has a highly positive correlation with HIF1α in lung adenocarcinoma and squamous carcinoma patients." (PMID 28423489, 2017). "Furthermore, we used publicly available datasets to validate that the late-stage lung adenocarcinoma patients showed higher expression HK2 and GBE1 than early-stage ones." (PMID 28423489, 2017). "Lastly, we found changes of some common pathways such as HIF1 signaling and metabolic pathways are involved in hypoxic-induced lung cancer cells; GBE1 and HK2 as independent unconventional clinical factors predicted survival in lung adenocarcinoma patients based on public microarray datasets." (PMID 28423489, 2017). "However, unlike lung adenocarcinoma, GBE1 knockdown increased oxidative phosphorylation in glioma cells and was difficult to reverse with FBP1 knockdown." (PMID 36900384, 2023). "Furthermore, a significant association emerged between expressions of GBE1/HK2 and the lung adenocarcinoma, but not lung squamous carcinoma in our analysis." (PMID 28423489, 2017).
lung carcinoma (8 papers, 2017 to 2025). "The convergence of HIF1 and HK2/GBE1 in the lung cancer patients with OSAS raises important questions regarding the underlying mechanism of OSAS-lung cancers." (PMID 28423489, 2017). "Similarly, in this study, we analyzed the microarray gene expression data (GSE30979) of ten patients with lung cancer via gene expression profiling analysis and biomedical gene information in the Cloud and found that GBE1 had a significant association with hypoxia." (PMID 32439898, 2020). "In this study, we found that hypoxia induced a significant increase in GBE1 levels in lung cancer cells." (PMID 32439898, 2020). "Decreased GBE1 expression directly affected not only the production of glycogen but also glucose metabolic signaling pathways, ultimately inhibiting lung cancer cell growth." (PMID 32439898, 2020). "Our previous study showed that glycogen branching enzyme (GBE1) is downstream of the HIF1 pathway in hypoxia-conditioned lung cancer cells." (PMID 31221150, 2019). "Our previous study showed that GBE1 is downstream of the HIF1 pathway in hypoxia-conditioned lung cancer cells." (PMID 31221150, 2019). "Our work presents evidence that alteration of HIF1 in lung cancer cells is associated with HK2 and GBE1." (PMID 28423489, 2017). "GBE1, while traditionally linked to glycogen metabolism, has emerged as a tumor progression factor through its involvement in NF-κB-mediated FBP1 methylation in lung cancer." (PMID 41049004, 2025). "Our previous study showed that glycogen branching enzyme (GBE1) is downstream of the hypoxia-inducible factor-1 (HIF1) pathway in hypoxia-conditioned lung cancer cells and GBE1 may be a critical regulator in the microenvironment of lung cancer." (PMID 31221150, 2019). "However, the mechanisms that drive GBE1 expression in lung cancer are still poorly understood." (PMID 32439898, 2020). "These proteins include LTN1 (ovarian cancer), GBE1, CACNA1E and ADCY10 (lung cancers), as well as PLEKHS1 and ADNP (bladder cancer)." (PMID 38951817, 2024). "HK2 and GBE1 are regulated by hypoxia-inducible factor (HIF), enabling lung cancer cells to invade tissues using focal adhesion kinase activity." (PMID 35747059, 2022). "We also observed that GBE1 and HK2 are downstream of HIF1 pathway important in hypoxia-conditioned lung cancer cell." (PMID 28423489, 2017). "We mapped metabolic network, and showed that expressions of GBE1 and HK2 significantly upregulated and highly correlated with expression of HIF1 in lung cancer." (PMID 28423489, 2017).
glycogen storage disease (7 papers, 2009 to 2024). "The glucan (1,4-alpha-) branching enzyme 1 (GBE1) was reported strongly associated with glycogen storage disease in previous research." (PMID 32258092, 2020). "A specific form of fatal glycogen storage disease was observed in a Quarter horse foal where a nonsense mutation in codon 34 of the glycogen branching enzyme (GBE1) was identified." (PMID 19664222, 2009). "Polyglucosan body disease (PBD) is a type of glycogen storage disease (GSD) and is mainly caused by mutations in eight different human genes, namely, GYG1, GBE1, RBCK1, PFKM, EPM2A, EPM2B (NHLRC1), PRDM8, and PRKAG2." (PMID 33413275, 2021).
glycogen storage disease IV (6 papers, 2021 to 2025). "Glycogen storage disease IV is associated with GBE1 gene mutations, which is an autosomal recessive disorder." (PMID 38592052, 2024).